MYD88 (MYD88 innate immune signal transduction adaptor)
Diseases named in the same sentence as MYD88 in open-access papers (continued):
Sharing a sentence is not in itself a finding about the gene and the disease.
colitis (continued). "Further detailed histopathological and molecular detection suggested that CMFPs exhibited good antioxidant capacities, and could better improve oxazolone-induced zebrafish colitis via activating the MyD88/NF-κB inflammatory signaling pathway." (PMID 36118767, 2022). "Regulation of the TLR4/MyD88/NF-κB signaling pathway may be an important mechanism for the treatment of colitis inflammation in mice." (PMID 35630568, 2022). "Overall, these results demonstrated that CMFPs could have better therapeutic effects on zebrafish colitis via activating the MyD88/NF-κB inflammatory signaling pathway, and thereby regulating inflammatory cytokines." (PMID 36118767, 2022). "Additionally, curcumin significantly downregulated CD11b+F4/80+TLR4+ macrophages and the protein levels of TLR2, TLR4, MyD88, NF-κBp65, p38MAPK, and AP-1 in colitis mice." (PMID 34567209, 2021). "Moreover, we found that MyD88 plays a crucial role in both colitis- and RANKL-induced differentiation of M cells." (PMID 35051090, 2021). "Hence, we concluded that myeloid differentiation factor 88 (MyD88) is an essential molecule for colitis- and RANKL-related differentiation of M cells." (PMID 35051090, 2021). "Notably, curcumin significantly decreased the percentage of CD11b+F4/80+TLR4+ macrophages and inhibited the expression of TLRs/MyD88 signaling molecules and their downstream proteins in colitis mice." (PMID 34567209, 2021). "TLR4 and MyD88 played a critical role in the development of DSS-induced colitis." (PMID 34925349, 2021). "Third, TLR/MyD88 signaling in mTECs is important for the proper development of thymic CD73–CD25+Foxp3+ Tregs since its abrogation resulted in a decreased number and the functionality of Tregs, associated with pathological effects in the mouse model of colitis." (PMID 32398640, 2020). "On the other hand, studies with the dextran sulfate sodium (DSS)-induced colitis model, antibiotics induced colitis model and Myd88-knockout mouse model all reach identical conclusions that CX3CR1+ dendritic cells have strong ability of migration to mLNs and antigen presentation." (PMID 32153586, 2020). "TLR4/MyD88 pathway and amelioration of the epithelial tight junctions might partly explain the beneficial effect of EA on colitis." (PMID 32419794, 2020). "Together, these data supported the fact that IG may improve inflammation in DSS-induced colitis through blocking the TLR2/4/MyD88/NF-κB signaling pathway." (PMID 32337275, 2020). "However, in the H. hepaticus-colitis model, MyD88-activation within innate cells leads to worse intestinal inflammation." (PMID 31699962, 2019). "Furthermore, MyD88-/- mice, in contrast with wild-type mice, are unable to respond to treatment with probiotic bacteria in the context of DSS-induced colitis, further highlighting the link between MyD88 and the gut microbiota." (PMID 31026259, 2019). "Although the reasons for these differences are not clear at present, it is worth mentioning that MyD88 deficiency in mice seems to increase susceptibility to DSS-induced colitis." (PMID 31026259, 2019). "This is consistent with different reports, which showed that DSS-induced colitis alone or combined with fungal colonization promotes overexpression of pro-inflammatory mediators that amplify the inflammatory cascade through NF-κB and Myd88 expression." (PMID 29463799, 2018). "Moreover, knockdown of MYD88 caused zebrafish to develop more severe intestinal lesions under TNBS exposure, suggesting that MYD88 has a protective role in pathogenesis of colitis." (PMID 28515725, 2017). "It is likely that helminth co-infection may accelerate such response through undefined mechanism(s), contributing to the development of fatal colitis in MyD88 knockout mice." (PMID 25010669, 2014). "Moreover, TLR signaling within IECs confers protection in acute DSS-induced colitis by increasing the expression of amphiregulin in a MyD88 and TIR-domain-containing adapter-inducing interferon-β (TRIF) dependent manner." (PMID 24886810, 2014).
colitis (continued). "In addition, deficiency of the gene encoding MyD88, positioned upstream of NEMO in the NF-κB signaling cascade, prevented colitis and demonstrates that TLR activation by the gut microbiota is essential for disease pathogenesis in this model." (PMID 24062746, 2013). "In contrast, activation of FXR rescued TLR9−/− and MyD88−/− mice from colitis." (PMID 23372731, 2013). "In two models of spontaneous colitis, mice genetically deficient in IL-10 or intestinal epithelial cell expression of NEMO (IKK-γ), it was shown that additional deletion of the TLR-signalling adaptor protein MyD88 prevented disease progression." (PMID 20161736, 2010). "Indeed, although dss-induced intestinal injury is worsened in Myd88−/− mice, spontaneous colitis observed in Il10−/− mice is attenuated in Il10−/−; Myd88−/− mice 17,18." (PMID 19672421, 2009). "Also, DSS-induced colitis is exacerbated in MyD88−/− mice, a critical adaptor protein involved in TLR-induced NF-κB signaling." (PMID 17611628, 2007). "Several animal experiments showed that deletion of MyD88 could not mitigate intestinal inflammation and even increased tissue susceptibility to colitis." (PMID 38946731, 2024). "Besides, the elimination of intestinal Proteobacteria in MyD88-suppressed mice by broad-spectrum antibiotics could also alleviate colitis severity." (PMID 38946731, 2024). "Indeed, Tlr4-/- and Myd88-/- mice are less sensitive to DSS-induced colonic inflammation, which could be due to the diminished immune responses to microbiota." (PMID 37215126, 2023). "Furthermore, mice with MyD88-deficient TECs, which exhibit a deficiency in the recruitment of CD14+moDC, also suffer from a decreased thymic Treg output and functionality, which renders the peripheral T cell repertoire prone to colitis induction." (PMID 32398640, 2020). "In summary, andrographolide sulfonates exert potent anti-inflammatory effects in colitis by targeting multiple pathways, including YAP, TLR4/MyD88/NF-κB, and p38 signaling." (PMID 40005997, 2025). "In the context of colitis, an inflammation of the colon, Lp. plantarum Q7 EVs downregulated TLR4 and MyD88 expression, eventually leading to NFkB-mediated anti-inflammatory effects." (PMID 40948864, 2025). "In the DSS colitis model, TLR4/MyD88 signaling consistently activates the IKK-NF-κB axis, thereby driving TNFα expression, potentially bypassing any inhibitory effects exerted by Bcl6." (PMID 40416976, 2025). "In conclusion, our findings revealed that SPARC, increased in CD patients and colitis mice, resulted in intestinal barrier damage by directly interacting with OTUD4, and activating the MYD88/NF‐κB/MLCK/MLC2 pathway." (PMID 39888301, 2025). "For example, EVs from L. plantarum Q7 reduced pro-inflammatory cytokines in the colon and serum of DSS-induced colitis mice, potentially through modulating the TLR4/MyD88/NF-κB pathway." (PMID 41301527, 2025). "Our findings revealed a significant increase in MyD88 and caspase-3 concentrations in DSS-induced colitis, which subsequently decreased after muscone treatment." (PMID 40452925, 2025). "It was reported that deletion of MyD88 in CD4+ T cells resulted in defective differentiation of Th17 and decreased secretion of interleukin (IL)-17 in mice with colitis." (PMID 38946731, 2024). "Tomisetron, a receptor antagonist primarily used for anti-emesis, has also been shown to inhibit the development of colorectal cancer by inhibiting inflammation in colitis and TLR4/MyD88 signaling." (PMID 38785969, 2024). "A similar observation was made in a colitis study in rats, where melatonin reduced the up-regulation of TLR4, MyD88, and NF-κB induced by trinitrobenzenesulfonic acid." (PMID 38255808, 2024). "In experiments involving LPS-stimulated macrophages and murine colitis induced by DSS, HM0539 reduced the pro-inflammatory activation of toll-like receptor (TLR) 4 and myeloid differentiation primary response 88 (MyD88)-dependent signaling." (PMID 38674738, 2024).
colitis (continued). "The mRNA levels of TLR4, MyD88, and NF-ĸB in the DSS-induced colitis group of this study were significantly higher than the normal control group." (PMID 39323474, 2024). "Reishi has been shown to reduce AOM/DSS-induced colitis and tumourigenesis by inhibiting the TLR4/MyD88/NF-κB pathway, improving intestinal flora dysbiosis, and increasing the production of short-chain fatty acids." (PMID 37790812, 2023). "Research has confirmed that EPP can alleviate colitis in rats by regulating Th17/Treg balance, suppressing the TLR4/MyD88/NF-κB signaling pathway, and modulating intestinal flora." (PMID 38231750, 2023). "Mechanisms of blockage of MyD88 signaling with the MyD88 inhibitor in preventing CAC development in mice need further investigation, and our studies showed that it is involved in reduced colitis and improved tumor immune microenvironment." (PMID 38110638, 2023). "Previous evidence shows that G. lucidum can improve intestinal flora dysbiosis and reduce AOM/DSS-induced colitis and tumorigenesis by inhibiting TLR4/MyD88/NF-κB pathway." (PMID 37790812, 2023). "The results suggested that Jat plays a protective role in DSS-induced colitis by regulating the intestinal barrier function and inhibiting the TLR4/MyD88/NF-κB signaling pathway." (PMID 36193153, 2022). "Our results demonstrated that melatonin-mediated MT2 inhibits Aeromonas-goblet cell interactions to restore the level of MUC2 production via LPS/TLR4/MyD88/GSK-3β/ROS/NF-κB loop, further improving colitis in SD mice." (PMID 35355860, 2022). "In rats with 5-fluorouracil-induced colitis, the TLR2/MyD88/NF-κB pathway is activated to speed up inflammation, whereas patchouli alcohol (PA) slows down colitis through TLR2/MyD88/NF-κB pathway inhibition." (PMID 36555481, 2022). "Overall, our study revealed that MT2-mediated MT suppressed Aeromonas coupling with goblet cells and restored MUC2 depletion by inhibiting the TLR4/MyD88/GSK-3β/β-catenin/ROS/NF-κB loop, ultimately improving SD-induced colitis in mice." (PMID 35355860, 2022). "Clostridium butyricum triggers IL-10 production from intestinal macrophages via the TLR2/MyD88 signaling pathway and prevents mice from DSS-induced colitis." (PMID 35967333, 2022). "Our data suggest that pretreatment with Rg1 and ADSC + Rg1 markedly decreases the levels of TLR4 and MyD88, as well as the expression of TNF-α, IL-6, IL-1β, IFN-γ, and IL-17A in the DSS-induced mouse model of colitis." (PMID 35729638, 2022). "Consistently, seminal work from Medzhitov's lab showed the crucial role of TLR4/MyD88 signaling for the maintenance of the intestinal homeostasis and barrier repair during acute DSS colitis in microbiota dependent manner." (PMID 34124086, 2021). "Naturally, the effects of curcumin on the regulation of TLRs signaling pathways in colitis mice were further investigated by Western blot analysis, including TLRs signaling molecules TLR2 and TLR4 and the downstream proteins MyD88, NF-κBp65, p38MAPK, and AP-1." (PMID 34567209, 2021). "Administration of α-TREM-1 alleviated colitis in mice and resolved dysbiosis, which required TLR4/Myd88 signaling." (PMID 33767714, 2021). "Consequently, CNQX can inhibit the intestinal inflammatory response in mice with colitis, inhibit the mucosal barrier injury, increase the expression of tight junction proteins (including occludin and claudin‐1) and decrease the expression levels of MyD88, TLR4 and MD2." (PMID 34184406, 2021). "In our data, pinocembrin remarkably suppressed the mRNA expression of TLR4, Myd88, iNOS, COX-2 and TNF-α, as well as the increased protein expression of TLR4 and phosphorylated NF-κB p65 in the colon of DSS colitis mice." (PMID 32687156, 2020). "In our results, we demonstrated that repeated EA intervention ameliorates DSS-induced colitis by suppressing proinflammatory mediators, including CRP, IFN-γ, TNF-α, and IL-6 through the TLR4 signaling via MyD88-dependent pathway." (PMID 32419794, 2020).
colitis (continued). "Moreover, even if the cross-talk among the entire microbiota and the TLR/MyD88 signaling on the ISCs is not yet well elucidated, it has been shown that MyD88−/− mice are more susceptible to acute dextran sodium sulfate- (DSS-) induced colitis and develop a more severe disease." (PMID 31089331, 2019). "Several kinds of TLR and MyD88 inhibitors have been developed, some of which have been applied in the therapy of MS, SLE, RA, and colitis." (PMID 31998072, 2019). "IEC specific deletion of MyD88, TRAF6, NEMO (regulatory subunit of the IKK complex) and IKKα/β led to impaired epithelial barrier function and enhanced DSS-induced colitis." (PMID 29570694, 2018). "Deficiency of TLR4 and MyD88 have been shown to sensitize and mice to DSS mediated colitis and previous studies have concluded that TLR4 and MyD88 are required for the control of bacterial translocation and triggering the repair of the intestinal epithelium." (PMID 29259211, 2017). "Our study provided evidence for the first time that baicalein attenuated TNBS-induced colitis, at least in part, via inhibition of TLR4/MyD88 signaling cascade as well as inactivation of NLRP3 inflammasome." (PMID 29180692, 2017). "We subsequently determined the possible involvement of TLR-4, MyD88 and NF- κB protein expression levels in the anti-UC effects of BR-SMEDDS in DSS-induced colitis mice by Western blotting analysis." (PMID 29078713, 2017). "MyD88 signaling is actually beneficial in the intestines, as MyD88−/− mice develop worsened DSS colitis." (PMID 26456940, 2015). "Analysis of mucosal damage score demonstrated that, with the exception of TLR4−/− mice which showed a less severe disease, the severity of the colitis was essentially similar in wild type, TLR2−/−, TLR9−/− and MyD88−/− mice (n = 6; p<0.05)." (PMID 23372731, 2013). "Since activation of TLR9 transduces its signal by recruiting the adaptor molecule MyD88 we have then investigated the role exerted by FXR on development of TNBS colitis in TLR9−/− and MyD88−/− mice." (PMID 23372731, 2013). "We have also demonstrated in an animal model of acute colitis using dextran sulfate sodium that TLR4, through the adapter protein MyD88, is important in the intestinal response to epithelial injury and limiting bacterial translocation." (PMID 20976181, 2010). "Recent findings in acute TNBS-induced colitis model in rats demonstrate that Curcumin-induced inhibition of intestinal inflammation involves TLR-4 and MyD88." (PMID 21151942, 2010). "It is plausible that Mycobacteria stimulate TLRs to promote colitis in IL-10-/- mice, which presents a scenario where mycobacterial recognition via TLR and MyD88 activate DCs to control Th1 polarization and expansion." (PMID 18533024, 2008). "Our study demonstrated that 4-PBA could relieve E. coli-induced colitis by improving gut microbiota structure and inhibiting the expression of pro-inflammatory cytokines through the TLR4/MyD88/NF-κB pathway." (PMID 40076603, 2025). "Further investigation was conducted to explore the possible explanation as to why inhibiting MyD88 did not alleviate the severity of acute DSS-induced colitis." (PMID 38946731, 2024). "Therefore, inhibiting the TLR4/MyD88/COX-2 signaling pathway in present study was shown to be a valuable approach for the prevention and improvement of colitis." (PMID 38611304, 2024). "MyD88 knockout (MyD88−/−) mice and the MyD88 inhibitor (TJ-M2010-5) were used to investigate the impact of MyD88 on acute dextran sodium sulfate (DSS)-induced colitis." (PMID 38946731, 2024). "Further blockade of the NLRs signaling pathway or elimination of gut microbiota with broad-spectrum antibiotics in DSS-induced colitis mice treated with TJ-M2010-5 ameliorated the disease severity, which was not improved solely by MyD88 inhibition." (PMID 38946731, 2024).
colitis (continued). "In our experiments, we found that treatment with ALA could significantly alleviate inflammatory intestinal injury by suppressing the MyD88/NF-κB pathway, further confirming the important role of ALA in the treatment of colitis induced by T. gondii infection." (PMID 38087373, 2023). "Given this background, our findings suggest that an internal link may exist between the suppression of inflammatory mediators, blocking of the TLR4/MyD88/NF-κB pathway, and restoration of intestinal barrier function in Jat ameliorate DSS-induced colitis." (PMID 36193153, 2022). "Furthermore, by blocking the TLR4/MyD88/GSK-3β/β-catenin/ROS/NF-κB loop, MT via the MT2-mediated pathway restored MUC2 depletion, ultimately alleviating the induced colitis in mice." (PMID 36421432, 2022). "Furthermore, protein expressions such as TLR4, MyD88, p–NF–κB-p65, NF-κB-p65, COX-2, ZO-1, and Occludin were detected to elucidate the molecular mechanism of Jat on DSS-induced colitis model." (PMID 36193153, 2022). "In addition, baicalein administration remarkably suppressed the phosphorylation of NF-κB p65 and IκBα in the colon of TNBS-colitis mice, which was in accordance with the inhibitory effects on the protein expression of TLR4 and MyD88." (PMID 35805952, 2022). "In addition, melatonin attenuates TNBS-induced colitis through a melatonin receptor-independent pathway in mice and relieves TNBS colitis through the TLR4/MyD88/NF-κB signaling pathway in rats." (PMID 35116024, 2021). "By comparison, in DSS-colitis ICR (institute of cancer research) mice, dietary supplementation with soy isoflavones (0.5% for 7 days) alleviated colitis severity and inactivated Myd88 but did not significantly alter TLR4 expression following colitis induction." (PMID 33916612, 2021). "This study showed that B. lactis XLTG11 could alleviate DSS-induced colitis in mice including regulating inflammatory cytokines, protecting intestinal barrier function, inhibiting TLR4/MYD88/NF-κB activation, and modulating the specific gut microbiota." (PMID 34683415, 2021). "In the colitis model, Myd88−/− CD4 T cells showed reduced survival, failed to induce severe disease, and poorly differentiated into Th17 cells." (PMID 32547564, 2020). "GSK-3β was found to strongly promote the production of proinflammatory cytokines by TLR-induced MyD88-dependent and MyD88-independent pathways, and the inhibition of GSK-3β was shown to protect the host from several inflammatory diseases such as colitis, arthritis, and sepsis-induced organ failure." (PMID 29849928, 2018). "In contrast, overexpression of the NOD2 gene rescued mice from peptidoglycan-induced colitis, and mice deficient in TLR9 and MyD88 no longer demonstrated probiotic-mediated inhibitory effects on intestinal inflammation in experimental colitis." (PMID 29892282, 2018). "In terms of the activation/expression of receptors and signaling pathways in response to C. glabrata sensing and colitis, MBL-C and Myd88 expression increased significantly, while the expression of TLR-4 and PPARγ decreased in the colons in response to C. glabrata ΔChs3." (PMID 29463799, 2018). "Our data suggest that IL-33 facilitates wound healing and ameliorates colitis via modulating the differentiation of goblet cells and M2 macrophages independent of the MyD88 pathway and T-cells." (PMID 28404987, 2017). "Previous studies that addressed an IEC-specific role of MyD88 using conditional MyD88 targeting in IEC have found little evidence for a prominent role of IEC-intrinsic MyD88 in colitis or infection with C. rodentium." (PMID 28520792, 2017). "In the current study, we observed that helminth co-infection in MyD88 knockout mice results in the development of fatal colitis, yet there was no clear evidence showing an increase in proinflammatory cytokine production in the infected colon tissue." (PMID 25010669, 2014).